IL10 (interleukin 10)
Diseases named in the same sentence as IL10 in open-access papers (continued):
Sharing a sentence is not in itself a finding about the gene and the disease.
infection (continued). "This analysis confirmed that during infection there was an upregulation of both Cd79a+Il10+ Bregs (p < 0.02, Mann–Whitney test) and Cx3cr1+Il10ra+ microglia (p < 0.01, Mann–Whitney test)." (PMID 38594373, 2024). "In Mtb infection, IL-10 is critical for downregulating the inflammation at the site of infection, reducing tissue damage via cell recruitment to the infected tissue." (PMID 38790916, 2024). "In contrast, hMDM infection with S. epidermidis 1457 induced a significantly higher expression of IL10 compared to S. epidermidis 1457-M10 and 1457ΔatlE." (PMID 39567551, 2024). "The observed imbalance between these proinflammatory cytokines and the anti-inflammatory cytokine IL-10, especially at later stages of infection, suggests a potential role in the perpetuation of inflammation and subsequent renal damage." (PMID 38787228, 2024). "When we analyzed the values of cytokines IL-6 and IL-10 based on the type of infection (primary or secondary) and the phase of infection, we observed an interesting pattern." (PMID 39457019, 2024). "Meanwhile, regulatory T lymphocytes (Tregs) play a suppressive role during infection, dampening excessive inflammatory responses through the secretion of anti-inflammatory cytokines such as interleukin 10 (IL-10) and transforming growth factor-beta (TGF-β)." (PMID 39770782, 2024). "In spring, infection induced upregulation of inos at 24 hpi, while upregulated expression of il-12p35, ifn-γ2, arginase 2 and il-10 was observed only in the spring both at 24 and 96 hpi." (PMID 38157099, 2024). "IL-4 enhances IFN-γ production in the late infection stage, while IL-10 inhibits inflammation and prevents CD4+ T cell-mediated severe immunopathology." (PMID 39597646, 2024). "After experimental infection, anti-inflammatory IL-10 production was increased as well as transcription factors to downregulate T-cell activation." (PMID 39019114, 2024). "NF-κB, TNF-α, and Il-10 levels increased in response to infection and decreased in response to various treatments, with the highest reduction in the group treated with combined NTZ citrus Cs/Ag NPs." (PMID 39065665, 2024). "Collectively, these outcomes demonstrate the need to determine the cross-regulatory networks involving IL-10, NO, and arginase for the design of therapies that modulate arginine metabolism to augment immunity to Mtb or other infections." (PMID 38922041, 2024). "At 72 h post‐infection, these cytokine/chemokine levels shifted with significantly lower IFNγ and IL‐4, significantly higher IL‐5, IL‐10, IL‐17a, and CCL‐5/RANTES, and comparable IL‐2 and TNFα levels." (PMID 37990641, 2024). "In support of the protective role of IL-10 after infection with Anaplasmataceae are the results of a recent study, which presented data on an increase in the concentration of serum IL-10 in dogs with ehrlichiosis after treatment with doxycycline." (PMID 39770719, 2024). "IL-10, an anti-inflammatory cytokine, plays a key role in limiting inflammation during infections by inhibiting pro-inflammatory cytokine production and reducing T cell activation." (PMID 39456722, 2024). "Inhibition of TLR9 resulted in slightly increased IL10 induction after infection with 1457-M10 and 1457ΔatlE." (PMID 39567551, 2024). "For example, certain Toll-like receptor (TLR) agonists, such as TLR2 and TLR4 agonists, have been shown to induce IL-10 production, leading to the dampening of inflammatory responses in infection models." (PMID 38251210, 2024). "Administration of GB before infection with T.b.r significantly reduced the anti-inflammatory cytokine IL-10 levels (p<0.05)." (PMID 38620045, 2024). "Most importantly, C57BL/6 mice with a deletion of the IL-10 gene were more resistant to infection than control mice and were equally resistant to infection as DBA/2 mice." (PMID 38535182, 2024). "To test the causative role of maternal systemic IL-10, we treated dams with recombinant IL-10 via intraperitoneal injection immediately after infection." (PMID 39484515, 2024).
infection (continued). "In symptomatic infection, the roles of IL-4 and IL-10 advance, reducing the effects of Th1 cytokines." (PMID 38399674, 2024). "In recent studies, the cytokine IL-10 was shown to stimulate the production of IgG 4 during infections." (PMID 39495782, 2024). "Cytokines tend to be markedly elevated, particularly IL-6 and IL-10, following co-infections in hematologic neoplasms, which has implications for predicting early infections and differentiating between G- from G+." (PMID 39559703, 2024). "For instance, INF-Υ and IL-10 are involved in HIV pathogenesis with production of INF-Υ and IL-10 across the course of infection." (PMID 39328992, 2024). "It has also been shown that IFN-γ and IL-10 are produced by peripheral blood mononuclear cells (PBMC) during both the intracellular persistent stage following infection and the active disease phase in both protected and aborted sheep." (PMID 39199857, 2024). "In contrast, in the setting of MCMV, expression of IL-27 and induction of IL-10 by Tr1-like cells contributed to viral persistence in the latent phase of the infection." (PMID 38966644, 2024). "The early phases of infection show a systemic decrease in pro-inflammatory cytokines (IL-1β, IL-6, and TNFα), accompanied by an increase in the anti-inflammatory cytokine IL-10." (PMID 39340101, 2024). "While other strains sensitive (rank of difference: 1.02; P=0.09), RifR (rank of difference: 1.22; P=0.1), and XDR (rank of difference: 1.98; P=0.07) showed a difference in IL-10 expression between 24 and 48 hr post-infection." (PMID 38800030, 2024). "The immune response has evolved to protect the host against infection; however, mechanisms such as the cytokine IL-10 are in place to regulate immune responses to pathogens and pathobionts to prevent untoward inflammation and host damage." (PMID 38609547, 2024). "On day 6 of infection, the study found elevated IL-4, IL-5, IL-13, and IL-10 levels in infected mice." (PMID 38166140, 2024). "NK cells can support angiogenesis in tumors and pregnancy and reduce T-cell overreaction to infection through IL-10 secretion to prevent tissue damage." (PMID 39511139, 2024). "CRP levels were also elevated in the anti-IL-10 treated animals at day 2 post-infection, as compared to controls." (PMID 38950078, 2024). "Animals receiving IL-10 blocking antibody had an increased number of lesions that were more metabolically active on day 6 post-infection, as compared to isotype controls or rmIFNγR1-Ig treated animals." (PMID 38950078, 2024). "In the setting of active infection, the role of IL-10—produced abundantly by various cell types—varies, offering either protection or harm to the host depending on the site of SA infection." (PMID 38786139, 2024). "In the 12-h infection sample, a decline in the number of cells was observed for all the macrophage types, which later at 18 h was followed by an increase in IL-10-expressing macrophage subtype." (PMID 38299832, 2024). "As ITA is an immunomodulatory agent, we measured the pro-inflammatory cytokines TNF, IL-6, and IL-1β, and the anti-inflammatory cytokine IL-10 in cell culture supernatants 24 hours after NMII infection of Acod1+/- and Acod1-/- BMM." (PMID 39156902, 2024). "This modulation creates a trade-off situation, wherein cytokine production, such as IL-2 and IL-10, is influenced while the microenvironment of infection is altered, ultimately enhancing the parasite’s chances of survival." (PMID 38455048, 2024). "In comparison to L. major, L. braziliensis induces significantly lower expression of IL-4, IL-10, and IL-13 in the early phase of infection in BALB/c mice." (PMID 38543944, 2024). "We also observed increased 18FDG uptake in the spleens of isotype control and anti-IL-10 treated animals, that peaked at ~day 10 post-infection and reached statistical significance over baseline." (PMID 38950078, 2024).
infection (continued). "Secondary infections, accounting for 38.2% of cases, exhibited earlier elevations of IL-6 and IL-10 than primary infections, suggesting that pre-existing immune memory primes faster cytokine release." (PMID 39457019, 2024). "Bacterial invasion immediately activates signaling pathways associated with inflammation to regulate the host immune response, while IL10 expression is significantly down-regulated in the early stages of infection." (PMID 39054472, 2024). "IL-10 levels increased with repeat SA infections, and was significantly amplified with AIsdB vaccination compared with IL-10 levels from naive mice vaccinated with AIsdB." (PMID 39681568, 2024). "Since IL-10 and TNF-α represent strong virulence factors of the fungus that increase host susceptibility to infection and resistance to treatment." (PMID 38321454, 2024). "At 30 dpi, animals administered the antibiotic cocktail and infected with the CL Brener strain exhibited a tenfold elevation in IL-10 production compared to the infection-only group (p < 0.0001)." (PMID 39597721, 2024). "In contrast, the cytokines IL-4 and IL-10 of the Th2 cells play a role in the advancement of the infection." (PMID 38667922, 2024). "For example, cluster 2 genes were upregulated at day 3 post-infection and began to decline by day 7 in control and anti-IL-10 treated animals." (PMID 38950078, 2024). "While expressing highly inflammatory mediators, macrophages also express anti-inflammatory mediators such as IL10 during infection." (PMID 38098020, 2023). "Once activated, iNKT cells promptly produce various cytokines, including IFNγ, TNFα and IL-10 which actively recruit and activate neutrophils, macrophages, NK cells, and other immune cells to the site of infection." (PMID 37965344, 2023). "In one study, the expression of TNF-α, IL-6, and IL-1β in THP-1 cells was increased significantly within 48 h after infection, whereas secretion of the anti-inflammatory factor IL-10 was inhibited." (PMID 37841250, 2023). "In the current study, we observed higher levels of serum IL-10 after five weeks in mice that had been depleted of Treg cells prior to infection with 1 × 103 B. burgdorferi organisms than in infected, Treg cell-sufficient mice." (PMID 36839461, 2023). "Studies show that host cells infected with C. trachomatis release this pro-inflammatory cytokine throughout the growth cycle of C. trachomatis which, along with the release of TNF and IL-10, leads to a poorer prognosis of the infection." (PMID 36897879, 2023). "IL-10 levels increased after infection and markedly upregulated in mice of Sj + anti-BAFF group (p < 0.01)." (PMID 37375483, 2023). "IL-10 is primarily produced by T helper cells, monocytes, and macrophages; however, it has been reported that epithelial cells and granulocytes are also able to produce IL-10 in response to infection or tissue damage." (PMID 36742292, 2023). "A further functional maturation analysis of DCs revealed that IL-27 signaling restricted the protein and mRNA expression of IL-10 from DCs following infection." (PMID 36985179, 2023). "As a result, when the IL-10/TNFα ratio is elevated, it leads to the recruitment of a higher number of macrophages and neutrophils that produce IL-10 at the infection site." (PMID 38196634, 2023). "The cytokine production was also manifested upon immunization; particularly, high levels of IFN-γ, TGF-β, and IL-10 were induced by the infection." (PMID 37243206, 2023). "Non-lymphoid organs harbour tissue-resident B cells that include a substantial population of B-1 cells and promote homeostatic anti-inflammatory macrophage polarization via IL-10, with profound effects on bacterial clearance during local infection." (PMID 37925420, 2023). "Collectively, these findings reveal a novel role for granulocyte-derived IL-10 in suppressing S. aureus clearance during craniotomy infection, which is one mechanism to account for biofilm persistence." (PMID 37179295, 2023).
infection (continued). "Myeloid DCs were present at very low frequencies (<2%), and not more than 70 total cells were detected to be harboring mRNA from TNF, IL6 or IL10 after infection." (PMID 37024448, 2023). "Conversely, a humoral immune response characterized by the production of anti-inflammatory cytokines, such as IL-10 in VL or IL-4 in CL, by CD4+ T helper cells (Th2) leads to susceptibility to infection." (PMID 37569710, 2023). "Within splenocytes, expression of IFNγ, TNFα, IL17, IL13, IL10, and TGFβ were changed by both infection and vaccination within CD4 and CD8 T cells and regulatory T cells." (PMID 36799886, 2023). "AUD cells also secreted three anti-inflammatory cytokines in response to infection: IL-1RA, IL-10, and IL-22." (PMID 37786945, 2023). "Meanwhile, IL-10, a cytokine with anti-inflammatory properties, plays a central role in infection by limiting the immune response and preventing damage to the host." (PMID 36677846, 2023). "Both the upper and lower airways responded to the infection by all VoCs, but with a tissue-specific inflammatory signature: in the lungs, Mx2, Il-6, Cxcl10 and Il-10 were upregulated for all VoCs, and the highest in SARS-COV-2 Wuhan-infected animals." (PMID 37495586, 2023). "IL-27 promotes PD-1/PD-L1 and IL-10 expression, and we found that it was upregulated in the monocyte population throughout the infection." (PMID 37920474, 2023). "At day 16 post-infection, IL-17 was impaired more obviously (p < 0.0001), while immunosuppressive cytokine IL-10 was enhanced significantly (p < 0.001)." (PMID 38029253, 2023). "A straightforward explanation is that the mechanism of feedback upregulated the anti-inflammatory response, which was consistent with the upregulated interleukin-10 (IL-10), an anti-inflammatory factor, post infection." (PMID 37256871, 2023). "During an infection, monocytes/macrophages acquire the M1 phenotype (IL-10-, IL-12+, NOS+, CXCL9+), which are the major effector cells for the first line of host antibacterial defense." (PMID 37600828, 2023). "IL-10 is an immunoregulatory cytokine produced by the activated T and DC cells to control excessive inflammation leading to the resolution of infection following clearance of the pathogen." (PMID 37208771, 2023). "In contrast to other Th cells in spleen, the Th IL10+ subpopulation was increased compared to controls throughout all three stages of infection, contracting at 8 weeks of relapse, although the overall % of Th IL-10+ cells was modest." (PMID 37898618, 2023). "Taken together, these data suggest that increased expression of proinflammatory cytokines along with decreased levels of IL-10 and IL-10-expressing macrophages in GB37-infected TLR2/4-deficient mice contributes to diminished ascending infection." (PMID 37747229, 2023). "A cross-sectional study from Nigeria showed a significant reduction of IL-10 and IL-6 in co-infected patients compared to TB mono-infection." (PMID 38089636, 2023). "In accordance with this theory, we discovered that Th2-type cytokines (IL-4 and IL-10) were notably increased in response to RHΔompdcΔuprt infection to balance the high production of Th1 cytokines." (PMID 37322556, 2023). "Infection induced equivalent levels of IL-10 at 4 dpi in both genotypes, which then rose dramatically in WT mice at 7 dpi, but this increase was significantly less in TLR7 KO mice." (PMID 37795093, 2023). "Intervention with IL-10 promotes bacterial clearance and inflammatory regression in the late stages of infection in transgenic mice." (PMID 38035330, 2023). "IL-10 is an anti-inflammatory cytokine which plays an important role in infection by regulating the immune response against pathogens and thus avoiding damage to the host." (PMID 37868351, 2023).
infection (continued). "In another study, upregulation of Th1 cytokines [IFN-γ, interleukins (IL)-2 and IL-12p40] and Th2 cytokines (IL-4, IL-5, IL-13 and IL-10) was thought to play a crucial role in driving cellular immune responses against IBDV in the acute phase of infection." (PMID 37744374, 2023). "Mice were examined at various intervals post-infection to quantify bacterial burden, leukocyte recruitment, and inflammatory mediator production in the brain and galea to assess the role of IL-10 in craniotomy persistence." (PMID 37179295, 2023). "Findings here demonstrate that Bhlhe40 plays an essential role in controlling infection with P. yoelii in mice by repressing IL-10 expression in T cells." (PMID 37843306, 2023). "It allows us to predict the probability that a patient will require hospitalization, intensive care, or mechanical ventilation, for which the blood IL-6 and IL-10 quotients during infection are calculated." (PMID 36979076, 2023). "Collectively, these findings establish the importance of granulocyte-derived IL-10 in preventing S. aureus clearance from the galea during craniotomy infection." (PMID 37179295, 2023). "In early septic shock, in addition to well established biomarkers of infection (C-reactive protein, ferritin, and procalcitonin levels), the cytokines IL-1β, IL-2R, IL-6, IL-8, IL-10, and TNF-α in plasma strongly increase." (PMID 37744876, 2023). "Intriguingly, after 30 days of infection, the levels of all cytokines decreased significantly over time, yet anti-inflammatory cytokines (IL-4, IL-5, IL-10 and IL-13) decreased to a lesser extent." (PMID 37691941, 2023). "In the meantime, anti-inflammatory cytokine IL-10 was significantly increased at 3 and 7 days post-infection." (PMID 37704783, 2023). "In the context of Tc infection, increased gene expression of innate immune responses and IFNγ and IL10 cytokines was noted in human placental explants exposed to Tc50." (PMID 38104118, 2023). "In general, these inflammatory mediators were more dramatically increased in IL-10 KO animals at day 7 post-infection, preceding the significant reduction in bacterial burden observed at day 14 in the brain and galea." (PMID 37179295, 2023). "Timely induction of IL-10 expression is critical for the disease progression by dampening the host inflammatory response to favor the survival of B. burgdorferi during early infection." (PMID 38011206, 2023). "We scored for IFN-γ, IL-12 p70, IL-1 β, TNF-α, IL-10, and IL-4 in their culture supernatants upon infection." (PMID 37928551, 2023). "Rhoptry kinase 16 (ROP16) a major virulence factor molecule produced by the parasite, can induce macrophages activation at an early infection phase through IL-4 and IL-10 expression stimulation, leading to a Th2- response promotion." (PMID 37389660, 2023). "IL-10 is crucial for host infection because it limits the immune response to pathogens and inhibits pro-inflammatory cytokine production." (PMID 37047694, 2023). "Levels of il10, which encodes the immune regulatory cytokine IL-10, significantly increased with infection plus imatinib at day 6 compared to infection alone, an effect recapitulated in measurements of IL10 protein levels." (PMID 37200402, 2023). "Whereas, IL-10, IL-13, and IL-33 were significantly increased in severe infection in compared a mild infection in children with HBoV." (PMID 37239461, 2023). "The cytokine IL-10 suppresses T-cell-mediated immunity, which is required to control infection with Plasmodium yoelii." (PMID 37843306, 2023). "Conversely, infection significantly reduced levels of IL-1α, IL-2, IL-9, IL-10, IL-12 (p70), IL-13, IFNγ, IL-3, CCL4 (MIP-1β), CSF 2 (GM-CSF), CCL5 (RANTES), and TNFα." (PMID 37790429, 2023). "In the present study, HD patients had a significantly higher percentage of regulatory T cells and tended to have higher IL-10 levels compared to control patients after breakthrough infection." (PMID 37515030, 2023).